IL2 (interleukin 2)
Diseases named in the same sentence as IL2 in open-access papers (continued):
Sharing a sentence is not in itself a finding about the gene and the disease.
melanoma (continued). "Fourth, melanoma cell-derived exosomal PD-L1 inhibits cytokine production and cytotoxicity of CD8+ T cells by decreasing the expression of GzmB and inhibiting the production of interleukin-2 (IL-2) and tumor necrosis factor (TNF)." (PMID 32322256, 2020). "For example, the ‘IL2 signaling events mediated by PI3K’ pathway (ngenes = 32) could predict the essentiality of BRAF in melanoma cell lines." (PMID 32620799, 2020). "In the past, we described that targeting SLAMF6 with its soluble ectodomain yielded CD8+ T cells that do not need IL-2 supplementation, either in vitro or in vivo, to eradicate established melanoma." (PMID 32122464, 2020). "As of 2016, intralesional IL2 is supported by NCCN clinical practice guidelines as an effective treatment for in-transit non-resectable melanoma." (PMID 32455916, 2020). "Two patients in the SBRT + IL-2 group and three patients assigned to the IL-2 monotherapy group have not required additional systemic or local treatments for their melanoma." (PMID 32467299, 2020). "This study also illustrates that SBRT + IL-2 has activity in patients after progression on IL-2 monotherapy, CPI or BRAF-targeted therapy, the latter of which are the current standards of care for patients with advanced melanoma." (PMID 32467299, 2020). "Between 1985 and 1993, research on immunotherapy with interleukin-2 (IL-2), a cytokine that promotes T cell growth, greatly progressed, with its approval by the Food and Drug Administration (FDA), in 1998, as the first immunotherapy for advanced melanoma." (PMID 31614947, 2019). "Evidence of an effective and durable immune response against cancer dates back more than three decades, as high-dose interleukin 2 (IL-2) therapy produced durable responses with few relapses among approximately 10% of patients with advanced renal cell carcinoma (RCC) and melanoma." (PMID 31101066, 2019). "Thus far, two cytokines are FDA approved as anti-cancer therapeutic agents—IL-2 against metastatic melanoma and kidney cancer and IFN-α as adjuvant therapy against stage III melanoma." (PMID 31575023, 2019). "Treatment of mice bearing established B16 melanomas with hRT + IL-2c was superior to hRT + uncomplexed IL-2 or hRT alone; IL-2c alone was not effective." (PMID 30808414, 2019). "NK cells were co-cultured with B16 melanoma cells for 18 h and then with IL2 in the presence or absence of rapamycin for a further 18 h." (PMID 31595191, 2019). "The anti-tumor potential of several cytokines such as interleukin 2 (IL-2), interferon γ (IFN-γ), granulocyte-macrophage colony-stimulating factor (GM-CSF), IL-12 and IL-18 have been evaluated for the treatment of canine melanoma patients." (PMID 29534457, 2018). "The addition of anti-IL-2 blocking antibody alone did not affect the ability of Teff to inhibit melanoma." (PMID 29843822, 2018). "Thus, it is possible that IL-2 treatment following M-ILP would enhance the number and cytotoxic function of T cells in melanoma patients." (PMID 30560089, 2018). "Low avidity TRP2 T-cells primed with IL-2 alone failed to control melanoma growth, and became tolerized within the tumor environment." (PMID 30400835, 2018). "The anti-CD20 monoclonal antibody (mAb) rituximab was administered in 15 patients with renal cell carcinoma and 6 with melanoma before treatment with low doses of IL-2 in a clinical trial, without conferring any beneficial effects." (PMID 28507802, 2017). "Among the 12 patients with BRAF mutant melanoma who received BRAF/MEK inhibitors, median duration on therapy was 8.0 months – suggesting that these therapies retain their efficacy in patients who progress on HD IL-2." (PMID 28923120, 2017). "In the Pmel-1 murine melanoma model, the majority of Pmel-1 CD8 αβ T cells expressing transgenic TCRs specific for the self/tumor specific peptide, gp10025–33 are naive when stimulated in vitro with the gp10025–33 peptide and either IL-2 or IL-15." (PMID 28239463, 2017).
melanoma (continued). "In early reports, it was shown that Th1 cytokine mRNA for CD3δ, lymphotoxin (TNF-β), and IL-2 were significantly elevated in the ten regressing melanomas compared to the ten non-regressing melanomas." (PMID 28060744, 2017). "Patients were treated with IL-2 and autologous TIL expanded from surgically resected melanomas." (PMID 29276510, 2017). "In melanoma, flow cytometry was applied to study mechanisms of effects of immunotherapies, such as a PD-1 protein blockade by monoclonal antibodies pembrolizumab or nivolumab, CTLA-4 blockade with ipilimumab or high-dose IL-2 therapy." (PMID 29236046, 2017). "Interleukin-2 is a T-cell growth factor with well characterized effects on growth and expansion of T-cell subsets particularly CD8+ T-cells and documented anti-tumor efficacy in advanced renal cancer and melanoma." (PMID 28923120, 2017). "Preclinical data suggests that RT can promote memory T-cell formation through release of cytokines and upregulation of MHC-1, providing rationale for a phase 1 study that combined 1-3 fractions of RT (20 Gy per fraction) with high dose IL-2 for patients with metastatic RCC and melanoma." (PMID 27660705, 2016). "IT Ipi/IL-2 given to patients with non resectable stage III and IV melanoma is well tolerated." (PMID 27391442, 2016). "Presence of IL2 did not influence melanoma cells as we found similar protein expression with or without (data not shown)." (PMID 27625650, 2016). "Our data indicated that dysregulated IFN-γ secretion by NK cells contributed to a significant defect in STAT1 but not STAT5 activation in patients with advanced melanoma in response to IL-2 stimulation." (PMID 27153543, 2016). "Patients with melanoma and RCC receiving HD IL2 were identified by ICD9 procedure code 00.15." (PMID 26799322, 2016). "Retrospective data from the National Cancer Institute consisted of more than 1000 patients with either melanoma or mRCC who were treated with HD IL-2 with or without other therapy from 1985 to 2000." (PMID 27891227, 2016). "HD IL-2 as an intermittent bolus infusion therapy has been tested in clinical trials for different tumor types and is FDA-approved for the treatment of metastatic renal cell carcinoma and melanoma." (PMID 27153543, 2016). "In vivo, A20 lymphoma tumors stained positively for IL-2 whereas B16 melanoma tumors were negative for IL-2." (PMID 27477778, 2016). "In this report, we sought to test the hypothesis that combination of high-dose IL-2 and CTLA-4 blockade could mediate more profound therapeutic activity using the B16 melanoma tumor model." (PMID 25992289, 2015). "A clinical trial testing the combination of high-dose IL-2 and ipilimumab is planned, including an assessment of CD8+ T and NK cell responses, and could represent a new treatment strategy for patients with melanoma." (PMID 25992289, 2015). "After injecting MO4 melanoma cells expressing OVA into kCYC and WT mice, CD11c+ DCs were isolated from draining LNs and spleen and cultured with RF33.70 cells, which react specifically with OVA to produce IL-2." (PMID 26098776, 2015). "Despite the absence of phase 3 studies, IL-2 was approved because of durable responses were observed, and at the time of approval there were no other better therapeutic alternatives in melanoma and RCC." (PMID 24855563, 2014). "The objective response among the patients who required no further therapy for their melanoma or RCC after IL-2 was predominantly CR or PR; however, some individuals had SD and a few PD." (PMID 24855563, 2014). "A randomized open trial was conducted to assess the effectiveness of TIL + IL-2 in patients with regional melanoma lymph node metastases, but without any detectable visceral metastases." (PMID 24741578, 2014). "IL-2 and IFN-γ have been used in immunotherapy in some tumors like malignant melanoma." (PMID 24967419, 2014).
melanoma (continued). "From the present data, it may be suggested that Foxp3 participates in tumor growth and the modulation of the IL-2, IFN-γ and TNF-α cytokines and CD25, and that it may play a role in the immunosuppression of melanomas, possibly via this pathway." (PMID 24179494, 2013). "Neurological symptoms observed in 2 other patients did not seem to be different than those observed in patients without melanoma brain metastasis treated with HD IL-2." (PMID 23762555, 2013). "Of note, there did not seem to be an increased morbidity associated with treating patients with melanoma brain metastasis with HD IL-2 compared to treating those without a history of melanoma brain metastasis." (PMID 23762555, 2013). "In this analysis, patients with melanoma brain metastases received HD IL-2 without treatment-related mortality." (PMID 23762555, 2013). "Ipilimumab reacts with CTLA-4 on melanoma cell lines and tissues and is able to trigger antibody dependent cellular cytotoxicity (ADCC) engaging FcγRIIIA on lymphocyte subsets such as primary NK cells, IL-2 activated NK and γδT cells." (PMID 23634660, 2013). "Although both active and passive immunotherapy have been pursued vigorously over the past few decades, no melanoma vaccine has proven effective, and only interleukin 2 therapy has led to durable remission in only 5–8% of patients treated." (PMID 23837445, 2013). "Mice that rejected the IL-2- or TNF-transduced B16 melanoma cells showed no lasting recall memory, even though an immune response rejected the initial IL-2- or TNF-transduced tumor cells." (PMID 22899945, 2012). "When living B16 melanoma cells were transduced with IL-2 or TNF and injected into mice, no tumor growth occurred as a result of CTL and NK becoming activated by those released cytokines." (PMID 22899945, 2012). "High-dose interleukin-2 (HDIL-2) therapy which produces overall response rates of 15% to 23% remains an effective and long-lasting treatment for metastatic renal cell carcinoma and melanoma." (PMID 22532866, 2012). "Moreover, adoptive transfer of in vitro activated pmel cells in conjunction with human gp100 viral vaccination, lymphodepletion, high dose IL-2, and/or TLR stimulation induces profound vitiligo and regression of established melanoma in recipient mice." (PMID 21911918, 2011). "Biological therapies including IFN-α have shown a real, but minimal, effect in malignant melanomas and the effects of IL-2, as a treatment for malignant melanoma, are not yet clearly defined." (PMID 20234362, 2010). "We therefore ascertained whether HemoHIM administration enhanced the production of IL-2 and IFN-γ in melanoma-bearing mice treated with cisplatin." (PMID 19292900, 2009). "We did not detect CD8+ T cells specific for these three melanoma peptide/MHC conjugates prior to DAB/IL2 administration in any of the examined seven patients (data not shown)." (PMID 18334033, 2008). "ISGs are also consistently expressed in melanoma metastases following the systemic administration of IL-2 independent of clinical outcome." (PMID 17222352, 2007). "This study examined whether recombinant IL-21 alone or in combination with low-dose IL-2 could improve the in vivo anti-tumor function of naïve, tumor-antigen specific CD8+ T cells in a gp10025–33 T cell receptor transgenic pmel murine melanoma model." (PMID 16772043, 2006). "Studies focusing on the use of nonspecific modulators of immune activity such as IL-2 have demonstrated that creditable clinical responses can be achieved in certain tumour types, including melanoma and renal cell cancer." (PMID 16251873, 2005). "We investigated the effects of interleukin-2 (IL-2) exposure on T-cell signal transduction molecules and apoptosis markers in tumour-infiltrating lymphocytes (TIL) isolated from 20 melanoma and 16 colorectal carcinoma metastases and expanded in vitro for therapeutic reinfusion." (PMID 12610520, 2003).
melanoma (continued). "In this retrospective study, we aimed to investigate whether there are differences in PFS and OS rates or safety profiles between T-VEC and intralesional IL-2 in a cohort of patients with non-resectable stage III melanoma." (PMID 40171522, 2025). "The observed increase in IL-2 levels among melanoma patients treated with Nivolumab is likely attributable to activation and expansion of CD4+ helper T cells and CD8+ cytotoxic T lymphocytes, which are principal producers of IL-2 following T-cell receptor engagement." (PMID 41020868, 2025). "The pegylated IL2 cytokine prodrug bempegaldesleukin also did not improve clinical outcomes when given in combination with the PD-1 CPI nivolumab in previously untreated patients with advanced melanoma." (PMID 39895413, 2025). "In a phase I/II study conducted by Seledtsov and coworkers, 40 patients with stage III/IV malignant melanoma were treated with a poly-epitopic xenogeneic DNA cancer vaccine prepared from murine B16 and LLC murine melanoma cell lysates, combined with subcutaneous recombinant IL-2 injection." (PMID 39872522, 2024). "Therefore, the clinical application of IL-2 therapy for the treatment of cancer patients is limited due to its toxicity and the activation of Treg cells; ICIs have taken its place as first-line immunotherapy for the treatment of metastatic RCC and melanoma." (PMID 39218982, 2024). "The study recruited dogs with histopathological diagnoses of oral malignant melanoma, generated their peripheral blood mononuclear cells, expanded them into predominantly non-B non-T cells via stimulations of IL-15, IL-2, and IL-21, and then re-infused the cells into tumor-bearing dogs." (PMID 38668417, 2024). "The protagonists in the field of immuno-oncology are certainly interleukin-2 (IL-2), the first cytokine FDA approved for therapeutic purposes, IL-12, -15, -21, and interferon alpha (IFN-ɑ), for a long time used for the treatment of hematological neoplasms, for renal carcinoma and melanoma." (PMID 35301281, 2022). "We show that cell-mediated local cytokine (IL-2) delivery can effectively overcome immune suppression, augmenting CAR T cells to efficiently clear multiple immune-excluded tumor models (pancreatic cancer and melanoma) that are otherwise nearly completely resistant to standard CAR T cell treatment." (PMID 36520915, 2022). "The authors showed that the newly engineered IL-2 caused reduced expansion of immunosuppressive T cells (Treg) in comparison to native IL-2 and led to a dose-dependent delay in tumor growth, both in colon cancer and melanoma mouse models, without immunogenicity and with reduced toxicity." (PMID 35891197, 2022). "However, when used at a low dose (1 x 106 IU/m2/day), IL-2 did not enhance the antitumor response in stage III/IV melanoma patients to a vaccine composed of the NY-ESO-1 CTA, the emulsifier Montanide, and CpG-B." (PMID 35651800, 2022). "In IL-2 therapy for melanoma, the absence of STAT1 was correlated with increasing clinical stage." (PMID 33511023, 2021). "Equally, injection of aAPC particles loaded with both IL-2 and anti-CTLA-4 outperformed conventional single-release aAPCs, efficiently promoted sustained ICI and IL-2 release as well as antigen-specific T cell activation and expansion, and inhibited tumor growth in a murine melanoma model." (PMID 32942725, 2020). "In the case of IL-2, it was approved for the treatment of advanced renal cell carcinoma and metastatic melanoma; regarding IFN-α, it was approved for the treatment of hairy cell leukemia, follicular non-Hodgkin’s lymphoma, melanoma, and AIDS-related Kaposi’s sarcoma." (PMID 32610601, 2020). "Once melanomas reach the advanced metastatic stage, systemic therapies using the first US Food and Drug Administration (FDA)-approved chemotherapeutic drug dacarbazine (DTIC) and high-dose interleukin-2 (HD-IL-2, FDA-approved in 1998) have become the mainstay of treatments." (PMID 32899183, 2020).
melanoma (continued). "Combination regimens of IL-2, interferon-α (IFN-α), and cisplatin-based combination chemotherapies, while showing high overall response rates with some durable remissions, failed to significantly improve survival rates for patients with advanced melanoma and were subsequently abandoned." (PMID 31182961, 2019). "Melanoma patients treated with this combination therapy also showed increased numbers of Tregs after four vaccinations, indicating that cyclophosphamide was not able to counteract the effect of IL-2 on Tregs, as IL-2 has the potency to increase Treg numbers." (PMID 31020037, 2019). "Moreover, we observed that in human melanoma xenograft, targeting SDC1 via scFv OC-46F2 enhanced the therapeutic efficacy of L19-IL2, an immunocytokine composed of an scFv specific for the angiogenesis-associated B-fibronectin isoform and IL2, inhibiting tumor growth and VM processes." (PMID 31443604, 2019). "This lack of directly targeting melanoma cells might help to rationalize the sobering results observed in melanoma patients treated with VEGFR2-specific CAR-T cells in conjunction with IL-2 (NCT01218867)." (PMID 31779130, 2019). "The synthetic IL-2R did not interact with native IL-2, could mediate IL-2R signaling, thereby leading to the selective proliferation of CTLs and regression of melanoma in mice." (PMID 30842774, 2019). "Indeed, combining antibodies with a form of IL-2 with extended circulation provided surprisingly robust control of B16 melanoma tumor growth, in the absence of any marked toxicity." (PMID 31114758, 2019). "It appears that combined two nonspecific immunotherapies (R-CIK and IL-2) may not improve the prognosis of stage III malignant melanoma patients." (PMID 28913367, 2017). "Patients with advanced melanoma often experience durable tumor regressions when they are reinfused with culture-expanded natural T-cells derived from their own tumor nodules, in conjunction with nonmyeloablative chemotherapy and high dose IL-2." (PMID 27974697, 2017). "Alternatively much of the prior therapy for the melanoma patients may have been in the adjuvant setting, such that prior treatment did not impact on effect of HD IL-2." (PMID 27714434, 2016). "Moreover, high levels of serum VEGF in patients with advanced melanoma was associated with poorer overall survival when treated with ipilimumab (anti-CTLA4 antibody) and also predicted lack of response to high-dose IL-2 therapy." (PMID 27330805, 2016). "One aspect of the importance of IL-2 is its use in immunotherapy for cancer; there are several studies demonstrating its effectiveness in treating human tumors such as renal cancer, metastatic melanoma, and murine tumors such as Ehrlich Ascites Tumor and B16F10 melanoma." (PMID 26347589, 2015). "The clinical benefit group developed autoimmune phenomena (melanoma patients), lower platelet nadir, and on average, received the same number of IL-2 doses as the no clinical benefit group, suggesting a response relationship to the patient’s baseline immune status." (PMID 25815245, 2015). "This may suggest that even if HD IL-2 does not lead to intracranial response in patients, it may be of benefit to patients with melanoma brain metastasis by treating their systemic disease." (PMID 23762555, 2013). "However in a phase II clinical trial oral saracatinib monotherapy in 23 patients with advance melanoma failed to produce any objective clinical response, although there was evidence of inhibited T cell function and reduced cytokine (IL-2) production." (PMID 24276125, 2013). "The aims of the present study were to analyze Foxp3 expression in B16F10 melanoma cells in vitro, to determine whether this expression was affected during tumor growth in a murine melanoma model and to correlate Foxp3 expression with CD25 expression, interleukin (IL)-2 production and tumor weight." (PMID 24179494, 2013). "IL-2 is of use in advanced melanoma and does not need complicated ICU facilities." (PMID 2803954, 1989).